IRX5 (iroquois homeobox 5)
Description:
Establishes the cardiac repolarization gradient by its repressive actions on the KCND2 potassium-channel gene. Required for retinal cone bipolar cell differentiation. May regulate contrast adaptation in the retina and control specific aspects of visual function in circuits of the mammalian retina (By similarity). Could be involved in the regulation of both the cell cycle and apoptosis in prostate cancer cells. Involved in craniofacial and gonadal development. Modulates the migration of progenitor cell populations in branchial arches and gonads by repressing CXCL12.
Synonyms: IRXB2; IRX-2a; HMMS
Tractability: No criterion of Open Targets' tractability assessment is met for any kind of drug.
Gene: Protein-coding gene on chromosome 16 (54,930,865 to 54,934,485, forward strand). Ensembl gene ENSG00000176842.
Subcellular location: Nucleus
Subcellular location (Human Protein Atlas): Nuclear speckles; Cytosol; Microtubules
Gene Ontology:
Molecular function: sequence-specific double-stranded DNA binding; DNA-binding transcription factor activity, RNA polymerase II-specific; RNA polymerase II cis-regulatory region sequence-specific DNA binding; DNA binding
Biological process: embryonic cranial skeleton morphogenesis; gonad development; cell development; neuron differentiation; regulation of transcription by RNA polymerase II; regulation of DNA-templated transcription
Cellular component: chromatin; nucleus
Genetic constraint (gnomAD): Loss-of-function variants: 8 observed, 34.97 expected, observed/expected ratio (o/e) 0.23, 90% interval 0.13 to 0.41. The upper end of that interval is the gene's LOEUF score, 0.41, which puts it in group 1 of 6, group 1 being the genes least tolerant of losing a copy. Missense variants: 635 observed, 668.62 expected, observed/expected ratio (o/e) 0.95, 90% interval 0.89 to 1.01. Synonymous variants: 359 observed, 319.08 expected, observed/expected ratio (o/e) 1.13, 90% interval 1.03 to 1.23.
Gene-disease validity (ClinGen):
ClinGen rates the evidence that IRX5 causes each of these diseases.
craniofacial dysplasia - osteopenia syndrome (autosomal recessive): Moderate.
Homologues: Orthologues: chimpanzee IRX5 (99% identical), macaque IRX5 (98% identical), pig IRX5 (98% identical), dog IRX5 (97% identical), rat Irx5 (94% identical), mouse Irx5 (93% identical), guinea pig IRX5 (86% identical), rabbit IRX5 (82% identical), tropical clawed frog irx5 (65% identical), zebrafish irx5a (65% identical), zebrafish irx5b (46% identical). Paralogues in human: IRX2 (47% identical), IRX3 (33% identical), IRX4 (30% identical), IRX1 (30% identical), IRX6 (26% identical), MKX (16% identical).
Diseases named in the same sentence as IRX5 in open-access papers:
IRX5 is named in the same sentence as 56 diseases in open-access papers, as found by Europe PMC text mining. Sharing a sentence is not in itself a finding about the gene and the disease. The quoted sentences say what the papers report.
Obesity (45 papers, 2015 to 2025). Accumulation of substantial excess body fat. "Recent studies suggest that Irx3 and Irx5, in association with intronic variants of fat mass and obesity-associated gene, are determinants of obesity." (PMID 37335434, 2024). "For example, the FTO SNP consistently associated with obesity in human studies leads to increased expression of IRX5 and decreased thermogenesis." (PMID 39403345, 2024). "In this sense, the presence of genetic variants in FTO associated with increased risk of obesity is also influencing higher IRX5 mRNA levels in adipocytes, causing decreased energy expenditure and increased lipid accumulation." (PMID 37019912, 2023). "Mutated FTO (rs1421085) interacts with Iroquois-class homeodomain proteins IRX-3 and IRX-5, which are also linked to obesity in humans and animals." (PMID 36839421, 2023). "IRX5 null mice had a significant anti-obesity phenotype associated with a dramatic loss of fat mass." (PMID 35428362, 2022). "For example, an obesity-associated FTO variant (rs1421085) was found to disrupt an ARID5B repressor motif in an enhancer for IRX3/IRX5 during adipocyte differentiation, increasing obesity risk." (PMID 30617125, 2019). "We identify a novel association that implicates the IRX5 gene region in obesity and compare our results with previously derived interaction data for the region." (PMID 26642925, 2015). "However, in the same study, mice homozygous for a new deletion mutation of Irx5 (Irx5Δ/Δ) exhibited early postnatal lethality, whereas heterozygous Irx5Δ/+ mutant mice were found to show an anti-obesity phenotype like Irx3 knockout mice." (PMID 34795556, 2021). "Furthermore, ∼20k-bp deletion spanning the orthologous obesity-associated interval of Fto in mice leads to down-regulation of both Irx3 and Irx5 in preadipocytes and developing hypothalamus." (PMID 34795556, 2021). "Although there are differences in the metabolic phenotypes depending on the models, Irx3- and Irx5-deficient mice are generally lean and display an anti-obesity phenotype with elevated energy expenditure due to adipose beiging (i.e., enhanced adipose thermogenesis) compared to wild-type controls." (PMID 34795556, 2021). "Besides their developmental functions, IRX3 and IRX5 have been highlighted as determinants of human obesity in connection with the intronic obesity risk variants of FTO, a gene in the vicinity of the IRXB cluster." (PMID 34795556, 2021). "Within this study, we aimed to assess whether the link between the FTO risk genotype and IRX3 and IRX5 expression in AT is related to the development of obesity and to alterations of AT biology in children." (PMID 27560134, 2016). "Similar pleiotropy was observed for FTO obesity variants on the dynamics and lineage-specific expression of distal genes such as IRX3 and IRX5." (PMID 35659055, 2022). "Large-scale clinical research studies demonstrated that a variant of FTO enhances the expression of IRX5 and IRX3 leading to excessive adipocyte differentiation and obesity." (PMID 35428362, 2022). "A notable example of a distally acting enhancer variant > 50 kb, is the obesity FTO locus variant rs1421085 regulating IRX3 and IRX5, which are 500 kb and 1,163 kb away respectively." (PMID 35365203, 2022). "Their studies confirm that variants in multiple enhancers within FTO obesity-associated regions regulate the expression of multiple genes (IRX3 and IRX5) in at least two obesity-relevant tissues (adipose and brain)." (PMID 35205324, 2022). "By genetically engineering Irx3 and Irx5 mice, the group showed the presence of an anti-obesity phenotype in Irx3 knockout and Irx5 heterozygous mice." (PMID 35205324, 2022). "Recent studies further demonstrated that two homeobox genes, IRX3 and IRX5, in the vicinity of FTO directly mediate the effects of obesity-risk variants of FTO on body mass and composition regulation." (PMID 34795556, 2021).
Obesity (continued). "By contrast, in T/T non-obesity risk (higher thermogenic potential) genotype individuals, the ARID5B repressor binds to this DNA site and thus blocks the expression of IRX3 and IRX5, allowing the formation of the browning adipocytes." (PMID 34895148, 2021). "Collectively, these studies suggest that obesity-associated variants of FTO regulate the expression of IRX3 and IRX5 in the hypothalamus and adipose tissue contributing to metabolic changes." (PMID 34795556, 2021). "Claussnitzer demonstrated that the presence of the homozygous C/C obesity-risk alleles in this FTO locus results in the expression of nearby genes IRX3 and IRX5, thus generating less thermogenic adipocyte phenotype." (PMID 34895148, 2021). "The FTO obesity variant circuitry, mediated through IRX3 and IRX5, has been linked to adipocyte browning in humans and thus to mitochondrial function." (PMID 34290091, 2021). "The proposed causal allele was shown to alter an ARID5B repressor motif, leading to activation of the distant IRX3 and IRX5 in adipocyte precursor cells, and pro-obesity consequences for adipocyte thermogenesis regulation [23•]." (PMID 28758174, 2017). "Actually, this particular SNP was reported to increase expression of IRX3 and IRX5 through 3D chromatin effects during preadipocyte differentiation, thereby enhancing the formation of energy-storing white adipocytes, lipid storage, and obesity development." (PMID 35051171, 2022). "As most clinical data have illustrated that the risk alleles of FTO are associated with increased energy intake, our data highlight hypothalamic postnatal neurogenesis regulated by IRX3 and IRX5 as a potential mechanism affecting leptin response in human obesity." (PMID 34795556, 2021). "As obesity-risk variants of FTO affect the expression levels of both IRX3 and IRX5, Irx3/5dHet mice serve as a preclinical model mimicking lower IRX3 and IRX5 expression levels in humans." (PMID 34795556, 2021). "Another super-enhancer, which is located on an obesity-risk associated locus of the intronic region of the FTO gene, was linked to the regulation of browning in subcutaneous fat by determining the level of IRX3 and IRX5." (PMID 32316277, 2020). "IRX5 is important for the advancement of obesity, but this gene may also link with insulin resistance." (PMID 30678306, 2019). "An obesity-associated SNP in intron 1 of FTO has been associated with decreased browning of white adipose tissue, which coincided with an increase in expression of IRX3 and IRX5 in preadipocytes." (PMID 26788058, 2015). "The interaction of the FTO gene SNPs with the Iroquois homeobox 3 (IRX3) and Iroquois homeobox 5 (IRX5), genes also associated with the development of obesity and an effector of the FTO variants, may jointly regulate adipogenesis and cause white adipose tissue browning in mice." (PMID 37200795, 2023). "Therefore, increased IRX5 expression as shown in PBC of children with low PA could be indicative of an altered adipocyte function and related with obesity predisposition." (PMID 37019912, 2023). "The fact that the obesity-associated FTO SNPs are intronic has led to the notion that the SNPs may affect obesity through influencing the expression of genes proximal to FTO in the locus, namely, RPGRIP1L, IRX3, and IRX5." (PMID 26788058, 2015). "Obesity research suggests that the FTO gene region alters the function of nearby genes (IRX3 and IRX5), which impact the involvement of fat cells in thermogenesis." (PMID 38746260, 2024). "IRX3 and IRX5 have emerged as a strong link between the non-coding genetic variations of the FTO gene and obesity." (PMID 34795556, 2021). "Experiments have shown that T>C base changes in rs1421085, an intronic variant of the FTO gene found in GWASs on obesity, is involved in the regulation of adipocyte thermogenesis by increasing the expressions of nearby IRX3 and IRX5, but not FTO." (PMID 32271837, 2020).
Obesity (continued). "The rs9939609 is in linkage disequilibrium with rs1421085 (T>C), which may lead to obesity through the disruption of AR1D5B- mediated repression of Irx3 and Irx5." (PMID 31622411, 2019). "Variants in this gene have previously been shown to associate with birthweight and the development of obesity and diabetes Their functional impact may be in modifying expression of the IRX3 and IRX5 genes, rather than FTO itself." (PMID 31616461, 2019). "Furthermore, by defining the genes/pathways regulated by Irx3 and Irx5 in RGL-NSCs as well as their interplays with the Notch, Shh and Fgf pathways should unveil new knowledge about postnatal remodeling of the hypothalamus and provide mechanistic insights in NSC biology and obesity." (PMID 34795556, 2021). "Regardless of whether the obesity-associated SNP affects FTO expression levels, these studies have clearly proven an important role of FTO in the regulation of body weight, independent of IRX3, IRX5, and RPGRIP1L." (PMID 26788058, 2015). "For instance, an obesity-related SNP found in the intron of the FTO gene was found to influence the process of adipocyte browning by regulating the activity of IRX3 and IRX5, rather than directly impacting FTO itself." (PMID 36837926, 2023).
colorectal cancer (9 papers, 2017 to 2025). A primary or metastatic malignant neoplasm that affects the colon or rectum. "IRX5 promotes metastasis via RHOA signaling in colorectal cancer and regulates WNT/β-catenin pathways, which intersect with FAT1-mediated Hippo signaling." (PMID 40672387, 2025). "Another colorectal cancer study discovered that IRX5 improved genomic instability in colorectal cancer cells as overexpressed IRX5 decreased tumor cell proliferation and promoted G1/S cell cycle arrest and senescent activity." (PMID 38584220, 2024). "Increased expression of IRX3 and IRX5 was found in the transition of intestinal adenoma to colorectal cancer, negatively regulating the DPp/TGF-ß pathway." (PMID 36980893, 2023). "IRX5 can promote the invasion and migration of colorectal cancer cells by inhibiting the RHOA‐ROCK1‐LIMK1 axis." (PMID 34060213, 2021). "IRX5 promoted the metastasis of colorectal cancer by regulating the RHOA pathway." (PMID 40672387, 2025). "The expression of IRX3 and IRX5 can downregulate TGF-β signaling in human colorectal cancer cells." (PMID 36980893, 2023). "Additionally, studies have shown that IRX5 can negatively regulate RhoA/ROCK1/LIMK1 signaling pathway to promote the metastasis of colorectal cancer cells." (PMID 34486491, 2021). "In addition, IRX3 and IRX5 have been reported to participate in the transition from intestinal adenoma to colorectal cancer by negatively regulating the Dpp/TGF-ß pathway." (PMID 33304380, 2020). "CRNDE has been reported to be a new serum-based marker for diagnosis and prognosis of colorectal cancer, and it can stimulate cell growth and chemoresistance of colorectal cancer cells via correlating with IRX5 or miR-181a-5p-mediated regulation of Wnt/β-catenin signaling." (PMID 29088774, 2017).
prostate carcinoma (7 papers, 2015 to 2026). A carcinoma that arises from epithelial cells of the prostate gland. "In prostate cancer, IRX5 play an vital role in regulating cell cycle and apoptosis and is expected to play a crucial part in tumor therapy." (PMID 30115812, 2018). "Transient knockdown of Irx5 resulted in cell cycle arrest in the G2/M phase and subsequent apoptosis in the hyperproliferative human prostate cancer cell line LNCaP in a vitamin D3-dependent manner." (PMID 27170637, 2016). "Although recent studies have reported that IRX5 protein is involved in regulation of the cell cycle and apoptosis in prostate cancer cells, little is known about the role of IRX5 in the adult vasculature." (PMID 27170637, 2016). "The gene IRX5 has been shown to be involved in apoptosis and cell cycle regulation in prostate cancer cells." (PMID 27777635, 2016).
acute myeloid leukemia (4 papers, 2022 to 2024). Acute myeloid leukemia (AML) is a group of neoplasms arising from precursor cells committed to the myeloid cell-line differentiation. "In contrast, sister homeobox genes IRX2, IRX3 and IRX5 are aberrantly activated in the corresponding malignancies acute myeloid leukemia (AML) and B-cell progenitor acute lymphoid leukemia." (PMID 39689089, 2024). "Using the myeloid TALE-code, we have recently detected physiological activity of TALE homeobox gene IRX1 exclusively in megakaryocyte erythroid progenitors (MEPs) during early myelopoiesis, and aberrant expression of IRX1, IRX3 and IRX5 in particular subtypes of acute myeloid leukemia (AML)." (PMID 36233173, 2022). "Moreover, aberrant expression of IRX homeobox genes IRX1, IRX2, IRX3 and IRX5 has been detected in hematopoietic malignancies, including B-cell precursor acute lymphoblastic leukemia (BCP-ALL), T-cell ALL, and some subtypes of acute myeloid leukemia (AML)." (PMID 36833225, 2023). "On the other hand, the closely related homeobox genes IRX2, IRX3 and IRX5 are aberrantly expressed in subsets of BCP-ALL and acute myeloid leukemia (AML) patients and cell lines." (PMID 39689089, 2024). "Accordingly, screening for aberrant IRX gene activities in acute myeloid leukemia (AML) revealed overexpression of IRX1, IRX3 and IRX5 in subsets of patients, identifying these genes as oncogenes for this type of malignancy." (PMID 36833225, 2023). "Analysis of public profiling data from acute myeloid leukemia (AML) patients revealed aberrant activity of IRX1 in addition to IRX3 and IRX5, indicating an oncogenic role for these TALE homeobox genes when deregulated." (PMID 35328612, 2022).
breast carcinoma (4 papers, 2019 to 2023). "Experiments showed that knocking down the IRX5 gene in the breast cancer cell leads to a decrease in cell survival." (PMID 33166290, 2020). "Interestingly, 1,25-dihydroxyvitamin D3 has been shown to negatively regulate IRX5 expression in both androgen-sensitive prostate and estrogen-sensitive breast cancer cell lines." (PMID 31475119, 2019). "Consistent with a role for IRX5 as a promoter of DNA damage repair, we find that IRX genes are upregulated in many cancer types and that there is a correlation between IRX5 and BRCA1 expression in breast cancer." (PMID 37084727, 2023).
Hamamy syndrome (4 papers, 2016 to 2024). "IRX5 has been implicated in Hamamy Syndrome (OMIM #611174), a recessive condition including craniofacial anomalies, myopia and cognitive problems." (PMID 38519481, 2024). "Two mutations in human IRX5 cause a recessive congenital disorder, Hamamy syndrome, resulting in skeletal abnormalities, osteopenia and severe cardiac defects." (PMID 35428362, 2022). "Our results also provide insight into the causes of the skeletal changes and mineralization defects seen in Hamamy syndrome patients carrying mutations in IRX5." (PMID 27453922, 2016). "Based on our findings, a role for IRX5 in cell cycle and DNA damage responses in epithelia should be considered as a disease mechanism in some of the Hamamy syndrome manifestations." (PMID 37084727, 2023). "Since the global loss of both Irx3 and Irx5 leads to cardiac phenotypes similar to those seen in Hamamy patients, we wanted to see if the decreased mineralization we found in Irx3flox/flox/Irx5−/−/Osx-Cre+ mice also reflected the clinical presentation of Hamamy syndrome patients." (PMID 27453922, 2016). "Irx3flox/flox/Irx5−/−/Osx-Cre+ mice that survive to 3–4 weeks of age have smaller femora and tibiae and appeared to have signs of bone fragility, which is consistent with reports of Hamamy syndrome patients developing bone fragility and long bone fractures later in life." (PMID 27453922, 2016). "More detailed analysis of Hamamy syndrome patients cells using a human induced pluripotent stem cell model may help demonstrate the dynamics of IRX3 and IRX5 interactions in Hamamy patient cells." (PMID 27453922, 2016).
glioma (3 papers, 2014 to 2019). A benign or malignant brain and spinal cord tumor that arises from glial cells (astrocytes, oligodendrocytes, ependymal cells). "CRNDE, shares bi-directional promoter with iroquois homeobox 5 (IRX5), which is adjacent at the opposite strand, have been demonstrated over-expressed in many specific regions of human brain, and also upregulated in gliomas." (PMID 27637083, 2016). "The remaining members of the top 10-upregulated genes, IRX5, KIAA0101, LBX1, and DTL, have been studied in other cancers, but have not been well-studied in glioma." (PMID 31475119, 2019).